CCR6 (C-C motif chemokine receptor 6)
Diseases named in the same sentence as CCR6 in open-access papers (continued):
Sharing a sentence is not in itself a finding about the gene and the disease.
tumor (293 papers, 2005 to 2026). "In the tumor microenvironment, CCL20 can cause the exhaustion of CCR6+ tumor-infiltrating T cells and concomitantly support the growth and metastasis of CCR6+ tumor cells." (PMID 38472446, 2024). "PPARδ increased Ccl20 level to chemoattract Ccr6+ immunosuppressive cells, including tumor-associated macrophages, myeloid-derived suppressor cells and T regulatory cells, but decreased CD8+ T cells in gastric tissues." (PMID 37572185, 2023). "Multiple studies have shown that CCL20 is expressed in tumor cells and tumor-associated macrophages, which can activate CCR6 on cancer cells in an autocrine manner, causing their migration and epithelial-to-mesenchymal transitio n." (PMID 35065633, 2022). "Previous studies have indicated that CCL20 secreted by tumor-associated macrophages (TAMs) activates the expression of CCR6 in tumor cells and then induces cell proliferation and migration, as well as epithelial–mesenchymal transition (EMT)." (PMID 35841069, 2022). "This CCR6+ Th subset has been implicated in the IL-17-mediated induction of pro-angiogenic factors in the tumor microenvironment." (PMID 36107259, 2022). "For instance, CCR6 expression has been described to associate with tumor cell migration and proliferation as well as tumor growth and lung metastasis formation in melanomas." (PMID 35269787, 2022). "The nonsynonymous variants detected in TBL1XR1 and CCR6 were based on the high VAF considered to be present in the majority of the tumor cells." (PMID 35205758, 2022). "Liberation of chemokines such as C-X-C motif chemokine 5 (CXCL5) and C-C Motif Chemokine Receptor 6 (CCR6) by primary tumor is associated with liver metastasis and worse prognosis." (PMID 33800796, 2021). "Under inflammatory conditions, chemokine CCL20, the ligand for the CCR6 receptor, which is associated with the attraction of CCR6+ tumor cells, is upregulated to liver." (PMID 33800796, 2021). "CCR6-deficient mice show significantly decreased tumour growth and tumour-associated vascularisation." (PMID 32601464, 2020). "Tumours grown in Ccr6-deficient mice (0.76 g ± 0.49 g) had a significantly reduced weight compared with tumours from wild-type mice (1.38 g ± 0.76 g)." (PMID 32601464, 2020). "The effects of CCL20 on endothelial cell migration and tumour-associated vascularisation were comprehensively analysed with chemotaxis assays in vitro and in CCR6-deficient mice in vivo." (PMID 32601464, 2020). "B16/F10 tumour cells, which express Ccl20, were subcutaneously injected into the right flank of wild-type and Ccr6-deficient C57BL/6 mice." (PMID 32601464, 2020). "To this end, we examined B16F10-tumour growth in bone marrow chimeras harbouring either a Ccr6-deficient immune system in a wild-type host or vice versa." (PMID 32601464, 2020). "NKp46+CCR6+CXCR5+ ILC3s with LTi properties are also enriched in tumor-associated tertiary lymphoid structures in human non-small cell lung cancer." (PMID 31507605, 2019). "Apart from a link to M2-like macrophage regulation, CCR6-expressing γδ T cells produce pathogenic IL-17, which aggravates colonic inflammation (and thereby perhaps tumor clearance), albeit in a mouse with a deleted TCRα gene." (PMID 31379820, 2019). "The inflammatory chemokine ligand 20 (CCL20) and its receptor CCR6 were found to be associated with tumor prognosis in some studies." (PMID 31852159, 2019). "CCL-20/macrophage inflammatory protein-3α derives from macrophages in numerous types of tumours, which causes the recruitment of CCR-6-expressing lymphocytes." (PMID 29695802, 2018). "In the absence of consideration of metabolic regulation, their data suggest that CCR6 influences pro-tumourigenic tumour-associated macrophage (TAM) recruitment to the tumour microenvironment." (PMID 27335323, 2016). "One study reported that tumor-associated macrophages recruit CCR6+ regulatory T cells to tumor mass and promote its development via enhancing the production of CCL20 in a CRC mouse model." (PMID 24559209, 2014).
tumor (continued). "In the present study, a high expression level of CCL20 and a low expression level of CCR6 in the rectal mucosa were correlated with the development of UC-associated neoplasia." (PMID 24179507, 2013). "Immunohistochemical analysis for CCL20 and CCR6 expression in the rectal mucosa was performed and the correlation between expression and the pathogenesis of UC-associated neoplasia was investigated." (PMID 24179507, 2013). "Scarff Bloom Richardson tumor (SBR) grade was the only clinico-pathological variable associated with CCR6 expression on tumor cells (expression was associated with higher grade, p = 0.002)." (PMID 21624121, 2011). "CCR6 was expressed on tumor cells and its expression was associated with shorter relapse-free survival in univariate but not in multivariate analysis, and its impact on overall survival was not statistically significant." (PMID 21624121, 2011). "Occasionally, expression of CCR6 was observed by tumour-associated macrophages, CCR6-positive immature DCs were observed within T cell clusters of the tumour border zone." (PMID 20969772, 2010). "Elevated CCR6 expression in tumor-associated Tregs correlates with OSCC progression." (PMID 41445742, 2025). "Similarly, Th17 cells expressing CCR6 were found to significantly increase in HCC tumor tissue, and the density of CCR6+ Th17 cells was associated with overall survival and disease‐free survival of HCC patients." (PMID 40145607, 2025). "Heightened CCR6 expression in tumor-associated Tregs is linked to tumor advancement." (PMID 39000453, 2024). "Increased levels of CCR6 expression in tumor tissue may be caused by infiltration of regulatory T cells (Tregs), which are known to inhibit antitumor effects." (PMID 37316552, 2023). "In addition, volume analysis of fpVCT datasets demonstrated that tumour volumes were significantly larger in wild-type mice than in Ccr6-deficient mice." (PMID 32601464, 2020). "In addition, tumours in Ccr6-deficient mice were smaller in volume and had less weight than tumours grown in a wild-type background, therefore confirming our in vitro findings." (PMID 32601464, 2020). "The tumours in Ccr6+/+ → Ccr6+/+ (1.27 g ± 0.82 g) and Ccr6−/− → Ccr6+/+ (1.8 g ± 1.25 g) mice showed comparative weights, whereas Ccr6+/+ → Ccr6−/− (0.61 g ± 0.48 g) mice presented with tumours of significantly lower weight comparable to Ccr6-deficient C57BL/6 mice." (PMID 32601464, 2020). "Our analysis of possible targets for CCL20 action within the tumour microenvironment implicated microvascular endothelial cells due to their high expression of CCR6 on their cell surface in vitro, and due to the observation of CD31+/CCR6+ vessels closely apposed to tumour tissue of patients." (PMID 32601464, 2020). "CCL20 is a component of the complex regulation of tumour-associated angiogenesis, and therefore its receptor CCR6 might represent a promising target for anticancer therapy." (PMID 32601464, 2020). "Our previous study investigated whether the expression of CCL20 and CCR6 was correlated with the development of UC-associated neoplasia in adult UC patients." (PMID 25691899, 2015). "The present study investigated whether an evaluation of CCL20 and CCR6 expression in the rectal mucosa would be useful for predicting the development of UC-associated neoplasia." (PMID 24179507, 2013). "In conclusion, the results of the present study suggested that an evaluation of CCL20/CCR6 expression in the rectal mucosa may be useful for the identification of high-risk patients with UC-associated neoplasia." (PMID 24179507, 2013). "Gut TH17 seems to be a potential source for tumor-associated TH17, where it could be homed to the tumor environment via CCR6/CCL20 axis and expand locally." (PMID 23316374, 2012). "Furthermore, tumor vascularization and growth were significantly decreased in CCR6-deficient mice." (PMID 39985603, 2025).
tumor (continued). "Therefore, given that CCR6 deficiency downregulates tumor progression, the CCL20-CCR6 axis could be a therapeutic target." (PMID 32707869, 2020). "Furthermore, immunohistochemical analysis of CD31-positive vessels in tumour sections revealed that there were fewer microvascular and macrovascular vessels inside the tumours from Ccr6-deficient mice (10 ± 8.95) compared with the tumours from wild-type mice (26 ± 21.7)." (PMID 32601464, 2020). "This CCL20 then binds to CCR6 on the cell surface, forming a self-reinforcing signaling loop that promotes tumor cell invasion and migration." (PMID 41614909, 2026). "The chemokine receptors CCR6, CCR7, CXCR3, CXCR4, CXCR5, and CXCR6 have the highest expression across lymphocytes, and CCR8, a known hallmark of tumour infiltrating Treg cells, is exclusively expressed on Treg cells." (PMID 39915477, 2025). "Within primary cutaneous melanoma specimens CCR6 is localized to the tumor area and CCL20 to the stroma." (PMID 39825956, 2025). "In recent years, research has confirmed that the CCL20/CCR6 axis plays a critical role in promoting tumor growth in the tumor chemokine network." (PMID 40145607, 2025). "This aligns with previous research showing CCR6's role in immune cell recruitment and its potential involvement in anti-tumor responses." (PMID 39781526, 2025). "The high specificity of CXCR5 and CCR6 for their cognate ligands minimizes off-target risks while exploiting their functional roles in recruiting and activating tumor-specific T cells within the TME." (PMID 40764989, 2025). "The results demonstrated that inhibiting the activation of this pathway effectively diminished CCL20 secretion in TAMs and hindered the recruitment of CCR6+ Tregs, consequently reducing the proportion of Tregs and impeding tumor growth." (PMID 39853961, 2025). "The released CCL20 recruits monocytes into the tumour microenvironment by interacting with its receptor, CCR6." (PMID 40913253, 2025). "In vitro and in vivo experiments validated the therapeutic potential of the CCR6-MM and R848 combination, demonstrating biocompatibility, macrophage polarization efficacy, and dual inhibitory effects on tumor growth and metastasis." (PMID 41625363, 2025). "CCL20, via the CCL20/CCR6 axis, has been documented to promote tumor progression in numerous different types of cancer, including breast, hepatocellular, colorectal, and lung." (PMID 40114916, 2025). "The mice treated with HER2-CAR T cells, either co-expressing or singly expressing CXCR5 and CCR6, exhibited significantly improved long-term tumor control compared to those in the Control-T and HER2-CAR T groups." (PMID 40764989, 2025). "Collectively, our findings suggest that the co-expression of CXCR5 and CCR6 confers a distinct advantage, providing synergistic anti-tumor effects over the single expression of either receptor in HER2-CAR T cells." (PMID 40764989, 2025). "This interaction facilitates the recruitment of CCR6+ Tregs by macrophages, subsequently leading to the suppression of the anti‐tumor activity of CD8+ T cells." (PMID 39853961, 2025). "Emerging evidence has shown that CCL20 and its receptor CCR6 are important players in endothelial cell-mediated tumor progression." (PMID 39985603, 2025). "We demonstrated that Gal1‐induced TAMs activated the CCL20 release via stimulating the PI3K/AKT/NF‐κB pathway, therefore triggering the recruitment of CCR6+Foxp3+ Tregs that impaired the anti‐tumor response of CD8+ T cells." (PMID 39853961, 2025). "The CCR4/CCR6 chemokine system score was lower in tumor regression grading (TRG) of grade 0/1 compared to patients with TRG2/3, suggesting that the CCR4/CCR6 chemokine system would be a potential biomarker." (PMID 39703499, 2024). "It has been reported that in a variety of cancers, CCR6+ tumor cells can migrate to CCL20 enrichment sites and promote tumor metastasis." (PMID 39324138, 2024).
tumor (continued). "In terms of T lymphocytes, these cells are recruited to the tumor site via the chemokine receptor 6 (CCR6) and chemokine ligand 20 (CCL20) axis." (PMID 38638433, 2024). "Other notable players include T helper 17 (Th17) cells, CD4+ T cells expressing CCR4 and CCR6, CD14+ dendritic cells (DCs) expressing CTLA4 and PD1, tumor associated fibroblasts that inhibit NK cell function, and neutrophils that attract macrophages and Tregs." (PMID 38638433, 2024). "The overexpression of CCL20 in normal tissues adjacent to adrenal metastases establishes a microenvironment that enhances the attraction of circulating tumor cells expressing CCR6 to the adrenal gland." (PMID 39328239, 2024). "High levels of CCL20 are secreted by tumor cells and KCs to which CCR6 expressed in Tregs gets attracted inducing the migration towards the tumor site." (PMID 38571964, 2024). "Previous studies have reported that the chemokine CCL20 facilitates the recruitment and retention of CCR6+Treg cells, thereby promoting tumor invasion and progression." (PMID 38311726, 2024). "For instance, it has been demonstrated that chemokine (C-C motif) ligand 20 (CCL20) derived from tumor cells interacts with chemokine receptor 6 (CCR6) highly expressed by CD19+ CD5+ B cells, potentially enhancing angiogenesis and promoting HCC development." (PMID 38791916, 2024). "CCL20, a CCR6 ligand, attracts CCR6-expressing Tregs, promoting tumor progression and unfavorable outcomes in HCC." (PMID 39000453, 2024). "Consistently, CCL20 expression has been confirmed to be tightly regulated by NF-κB and of special importance in facilitating tumor growth and metastasis through interacting with CCR6 in CRC." (PMID 38228802, 2024). "Th9 cells are known to elicit strong host antitumor CD8+ cytotoxic T lymphocyte (CTL) responses by promoting Ccl20/Ccr6-dependent recruitment of dendritic cells to tumor tissues via IL-9 production." (PMID 39187636, 2024). "Data retrieved from TCGA and GTEX revealed significantly higher expression levels of the CCR6 in various tumour tissues compared with normal ones at the mRNA level, especially in HCC (p < 0.001)." (PMID 38493218, 2024). "High PBK expression affects the downregulation of CCR6 preventing cells such as effector/memory T cells and DCs from being attracted into the tumor for further tumor immune escape." (PMID 37993518, 2023). "Our findings confirmed that PD1 blocking and CCR6 can enhance the anti-tumor function of EGFR CAR-T cells in an NSCLC xenograft model, providing an effective treatment strategy to improve the efficacy of CAR-T in NSCLC." (PMID 36982500, 2023). "Compared with healthy individuals, CCL20 levels were higher in BC, attracting immune cells that express CCR6 near the tumor." (PMID 37373025, 2023). "A previous study has indicated that circulating pDCs in patients with melanoma substantially express CCR6 and migrate to tumor sites by binding tumor cell-derived CCL2060." (PMID 37817484, 2023). "Plasmacytoid DCs were proposed to be attracted to the tumor microenvironment through the CCL20/CCR6 axis or the hypoxia and hypoxia inducible factor-1α (HIF-1α) pathway." (PMID 37958800, 2023). "P38 was significantly activated through the CCL20/CCR6 axis, and then p38 played a signal transduction function to modify the miRNA spectrum, thereby creating conditions for the metastasis of tumor cells." (PMID 36447119, 2023). "Collectively, CD8 T cell infiltration and exhaustion status, CCL4 and CCR6 expression are different immune components that were affected by the CDKN2A genetic alterations in a way that finally enables tumor growth and progression." (PMID 37626750, 2023). "A significant positive correlation was found between the expression level of CCR6 and miR-150 in tumor tissue (p = 0.035, rho = 0.386, Spearman’s rank correlation)." (PMID 37316552, 2023).
tumor (continued). "These alterations modulate several immune components, including the infiltration and the exhaustion status of the CD8 T cells in addition to the expression of the chemokine CCL4 and the chemokine receptor CCR6 to finally potentiate the tumor growth." (PMID 37626750, 2023). "Higher expression level of CCL20 mRNA but lower expression level of CCR6 mRNA were observed in tumor in comparison to control tissue." (PMID 37316552, 2023). "CCR6 is a chemokine receptor that promotes tumor growth through the recruitment of tumor-promoting macrophages." (PMID 37626750, 2023). "Instead, CCR6 alone was as efficient or even more efficient in directing T cells into the tumor as was dual transduction with CCR6 and CXCR1 or CCR6 and CX3CR1." (PMID 37301772, 2023). "When CCL20 is secreted in tumor tissues, it attracts CCR6-expressing Treg cells, which are involved in tumor progression and poor prognosis." (PMID 37218898, 2023). "A lower expression level of CCR6 mRNA was noticed in tumor tissue compared to the control tissue (median RQ: 7.813 and 12.408, respectively), but this difference was statistically insignificant (p > 0.05, Mann–Whitney U-test)." (PMID 37316552, 2023). "It should be pointed out that it is the first such report of CCR6 mRNA expression level change in tumor tissue of NSCLC patients related to smoking." (PMID 37316552, 2023). "We noticed that the level of CCR6 mRNA expression negatively correlated with the growth of the tumor; however, the expression level of CCL20 mRNA was higher in larger tumors (T3 + T4 vs. T1 and T2)." (PMID 37316552, 2023). "Instead, organ infiltration and therapeutic efficacy were largely dependent on transduction with CCR4 in the lymph node-homing batch and CCR6 in the tumor-homing batch." (PMID 37301772, 2023). "Transduction with CCR6, a chemokine receptor known to recruit immunosuppressive myeloid cells and Treg into the tumor, showed the best efficacy." (PMID 37301772, 2023). "Meanwhile, CCL20 produced by tumor-promoting macrophages promotes CAC progression by recruiting CCR6+ B cells and γ δ T cells." (PMID 35935996, 2022). "Ingestion of EPS-R1 significantly increased the number of CCR6+ population in CD8+ tumor infiltrating lymphocytes (TILs)." (PMID 35956752, 2022). "Spleen resident ILC3 (both CCR6+ and CCR6-population) displays significant anti-tumour effects when stimulated by IL-12." (PMID 35557940, 2022). "Increased levels of miR-21 in tumor tissues from a murine breast cancer model reportedly stimulate the proliferation of CCR6+ Tregs." (PMID 36189271, 2022). "On the contrary, CCL20 deficiency counteracted the increased population of CCR6+ CD8+ T cells and attenuated the anticancer effect of the combined treatment of ICB and EPS-R1 in tumor-bearing mice." (PMID 36726985, 2022). "Deletion of CCR6 (CCL20 receptor) decreases macrophage infiltration and is associated with reduced tumor burden in diminished formation of intestinal adenoma formation in a model of sporadic intestinal carcinogenesis (APCMIN/+ mouse model)." (PMID 35935996, 2022). "The RORγt agonist promoted Type 17 T cell migration by upregulating CCL20 and CCR6 expression as well as Type 17 T cell tumor infiltration, improving the efficacy of anti-PD-1." (PMID 35459193, 2022). "Numerous studies have indicated that CCL20 derived from macrophages activates the expression of CCR6 in several tumor cells and then induces cell proliferation and migration, as well as EMT." (PMID 35841069, 2022). "Studies have shown that CCL20 derived from tumor cells interacts with CD19CD5 B cells overexpressed by CCR6 to promote the development of HCC, possibly through enhanced angiogenesis." (PMID 34869376, 2021). "The role of the CCL20/CCR6 pathway in tumor immunity is a controversial topic in light of current known studies." (PMID 34966384, 2021). "These CCR6+ TA-Tregs present a higher suppressive activity that increases with advanced tumor stages." (PMID 33924428, 2021).